ENSG00000260583 (novel transcript, antisense to MRPL39)
Synonyms: C21orf71; PRED21; LINC00515
Gene: Long non-coding RNA gene on chromosome 21 (25,582,770 to 25,583,326, reverse strand). Ensembl gene ENSG00000260583.
Diseases named in the same sentence as ENSG00000260583 in open-access papers:
ENSG00000260583 is named in the same sentence as 5 diseases in open-access papers, as found by Europe PMC text mining. Sharing a sentence is not in itself a finding about the gene and the disease.
ENSG00000260583 shares sentences with these, for which no sentence is quoted: glioma (2 papers); multiple myeloma (2); cancer (1); oligohydramnios (1); serous ovarian cancer (1).